S100B (S100 calcium binding protein B)
Diseases named in the same sentence as S100B in open-access papers (continued):
Sharing a sentence is not in itself a finding about the gene and the disease.
psychosis (14 papers, 2010 to 2025). "Overall, we revealed that psychotic disorders are associated with increased CSF-to-serum albumin ratio, and increased blood S100B, MMP-9, and zonulin." (PMID 37692299, 2023). "A published abstract on patients at risk of psychosis revealed an interaction between blood brain barrier permeability status, as measured by S100B levels, and larger hippocampal volumes in anti-neuronal antibody-positive patients." (PMID 31896766, 2019). "Our aim was to assess S100B-associated alterations in brain structure in the context of increased risk (patients and siblings) and disease-effects (patients) pertaining to psychotic disorder." (PMID 28358925, 2017). "This is the first study to investigate serum S100B as a marker of familial risk of psychotic disorder." (PMID 24358202, 2013). "Previously, we investigated serum protein S100B as a marker of familial risk of psychotic disorder." (PMID 28358925, 2017). "In other words, we tested whether a potential association between S100B and brain measures was moderated by psychosis risk." (PMID 28358925, 2017). "Associations between familial risk of psychotic disorder and S100B were examined." (PMID 24358202, 2013). "First-episode psychosis is marked by a consistent increase in serum and CSF concentrations of S100B, a calcium-binding protein that is released into the extracellular space following astrocytic membrane disruption." (PMID 40896232, 2025). "Specifically, reduced ALPS index values in patients relative to non-psychiatric controls align with a growing body of literature implicating astrocytic dysfunction, AQP4 misregulation, and elevated peripheral S100B levels in the acute phase of psychosis." (PMID 40896232, 2025). "Serum levels of S100B were also significantly correlated with the severity of SI among adolescent subjects with psychosis or affective disorders." (PMID 39451987, 2024). "Blood S100B was also elevated in psychosis, with a large effect size (SMD, 0.88; 95% CI, 0.59–1.17; p < 0.001), which remained significant after excluding 3 outlier studies (SMD, 0.70; 95% CI, 0.44–0.96; p < 0.001)." (PMID 37692299, 2023). "In MDD and psychosis, serum S100B levels positively correlate with the severity of suicidality, independent of psychiatric diagnosis." (PMID 23547920, 2013). "Elevated S100B levels correlate with paranoid and negativistic psychosis, impaired cognition, poor therapeutic response and duration of illness." (PMID 23547920, 2013). "We studied the potential association between serum S100B and neuroimaging markers in patients with psychotic disorder, their non-psychotic siblings and controls." (PMID 28358925, 2017). "As this is the first study to investigate an association between S100B and cerebral structural measures in psychotic disorder, no comparison can be made to previous work." (PMID 28358925, 2017). "Whether S100B in psychotic disorder mirrors pathophysiological mechanisms (which elicit exacerbation of disease) or compensatory action is unclear." (PMID 28358925, 2017). "Whether S100B in psychotic disorder mirrors pathophysiological mechanisms (which elicit exacerbation of disease) or compensatory action is unclear, as is its validity as a proxy marker for brain status." (PMID 28358925, 2017). "In the current sample in- or exclusion of all psychiatric morbidity in siblings and controls yielded the same results: the absence of association between serum S100B and risk of psychotic disorder." (PMID 24358202, 2013). "Second, the absence of group differences in S100B levels does not rule out an association between S100B and brain measures, that may or may not be moderated by psychosis risk." (PMID 28358925, 2017). "The association between S100B and brain measures was not moderated by psychosis risk." (PMID 28358925, 2017).
psychosis (continued). "Apart from changes in S100B, MDD patients also exhibited elevated levels of soluble GFAP in the cerebrospinal fluid (CSF), while anti-GFAP autoantibodies were found in depressed patients with psychosis." (PMID 39451987, 2024). "Elevated S100B serum levels in 28 children and adolescents with first-episode psychosis compared to eight healthy controls were reported, with no further analyses with clinical factors." (PMID 37759935, 2023). "The consistent elevation of blood S100B across treatment statuses in psychosis suggests the contribution of non-pharmaceutical factors, for example, pathological processes inherent to the disorders." (PMID 37692299, 2023). "Nor was S100B elevated in patients with psychotic disorder in our samples (including patients generally not in an acute stage of the disorder, with a mean illness duration <10 years)." (PMID 28358925, 2017). "To date, the validity of S100B as a proxy marker for white and grey matter status has not been investigated in patients with psychotic disorder or other psychiatric morbidity." (PMID 28358925, 2017). "Our findings suggest the following: i) S100B is not an intermediate phenotype of psychotic disorder; and ii) S100B is not elevated in the “general population” of individuals with psychotic disorder." (PMID 24358202, 2013). "The data did not suggest that serum S100B is an intermediate phenotype for psychotic disorder." (PMID 24358202, 2013).
glioblastoma (13 papers, 2008 to 2024). The most malignant astrocytic tumor (WHO grade IV). "In fact, treatment with EGTA in a serum-free medium has been reported to cause an increase in S100B secretion from the U87 glioblastoma cell line." (PMID 38068900, 2023). "Furthermore, inferred chromosomal copy number alteration (CNA) analysis of hallmark genetic alterations in glioblastoma confirmed the Nestin/S100B and CD45− marker definition to capture the majority of malignant cells of patients in which these hallmark CNAs were detected." (PMID 39304781, 2024). "In vitro studies involving cell lines derived from malignant glioblastoma shown that the attenuation of S100B expression decreased the number of invading cells whereas upregulation resulted in an increase in invading cells." (PMID 37377888, 2023). "Based on the immunocytochemical validation criterion of a coexpression of GFAP and S100B, 15 out of these 16 cell lines (94%) were defined as primary glioblastoma cell lines (pGCL)." (PMID 33251771, 2021). "Fifteen out of the 16 primary cell lines (94%) were characterized, retained the expression of GFAP and S100B as reliable markers of astrocytic or glial cells, and were defined as primary glioblastoma cell lines (pGCL)." (PMID 33251771, 2021). "As validation criterion, we have defined that all cell lines with an immunopositivity for both markers GFAP and S100B are primary glioblastoma cell lines (pGCL)." (PMID 33251771, 2021). "Since healthy cells of the brain parenchyma cannot be cultured under these cultivation conditions, GFAP and S100B can be used as markers for tumor cells in primary glioblastoma cell lines." (PMID 33251771, 2021). "Expression of S100B was highest in glioblastoma, followed by skin cutaneous melanoma (SKCM)." (PMID 36899866, 2023). "However, large S100B-containing vesicles were described in U373 and S100B-transfected U87 glioblastoma." (PMID 38068900, 2023). "The S100B immunoreactivity was observed in many glioblastoma multiforme 17,18." (PMID 33391433, 2021). "Applying the defined validation criterion, expression of both markers GFAP and S100B, 15 primary glioblastoma cell lines (pGCL) could be establish from 34 intraoperative glioblastoma samples processed in this study, resulting in a total efficiency of 44%." (PMID 33251771, 2021). "Therefore, the expression of malignancy and proliferation markers in combination to the proportion of GFAP and S100B expression should be assessed to define the usefulness of self‐established glioblastoma cell lines for further experiments." (PMID 33251771, 2021). "In vitro analysis showed S100B gene in the signature promoted glioblastoma (GBM) cell proliferation and migration." (PMID 34712325, 2021). "The interaction between S100B and tau was further confirmed by colocalization analysis in live and fixed cells in experimental setups not dependent on BiFC, as demonstrated by experiments using HeLa cells, U-251 MG glioblastoma cells, and differentiated SH-SY5Y neuroblastoma cells." (PMID 34725360, 2021).
colorectal cancer (12 papers, 2012 to 2024). A primary or metastatic malignant neoplasm that affects the colon or rectum. "Analysis showed that the aptamer-based antagonist inhibited proliferation and migration of colorectal cancer cells induced by S100B." (PMID 34035661, 2021). "Therefore, studies should explore novel specific therapeutic agents targeting S100B/RAGE/NFκB axis to block development of colorectal cancer." (PMID 34035661, 2021). "In addition, Apt-RAGE inhibited S100B-dependent activation of proliferation and migration of colorectal cancer cells, which are critical events for cancer cells to adapt to the TME during tumor progression." (PMID 34035661, 2021). "Further, we explored the role of S100B on proliferation and migration of colorectal cancer cells." (PMID 34035661, 2021). "Intranasal insulin may decrease the risk of POCD and inhibit the elevated serum IL-6, TNF-α, and S100β levels in elderly patients after laparoscopic radical resection of colorectal cancer, which proves that intranasal insulin may be a promising therapeutic option for POCD." (PMID 38915348, 2024). "This study explored the role of the S100B/RAGE signaling on cell viability, migration, and angiogenesis and progression of colorectal cancer." (PMID 34035661, 2021). "In a previous study from our group, S100B release was strongly increased in chronic gut inflammation, and this might, in turn, offer mechanistic insights into the transition from chronic inflammatory conditions, such as ulcerative colitis (UC) to colorectal cancer." (PMID 31266264, 2019).
glaucoma (12 papers, 2018 to 2025). Increased pressure in the eyeball due to obstruction of the outflow of aqueous humor. "The data presented here, however, suggest that a preconditioning state exists prior to the activation of astrocytes in our experimental models of glaucoma, and that this is associated with S100B." (PMID 39908332, 2025). "For each of the 4 clusters, notable genes associated with glaucoma, neuroinflammation, or reactive astrocytes were: Cluster 1 (Nrf2, Hspb1, S100β), Cluster 2 (Ptgs2, Clcf1), and Cluster 4 (C2, Tlr4, Lcn2, H2-T23, Thbs1, Il6ra)." (PMID 37759301, 2023). "Exogenous insertion of S100B (used as an ocular antigen) in the glaucoma model caused a loss of RGCs (Retinal Ganglion Cells) and degeneration of the optic nerve after 28 days of the window, without intraocular pressure." (PMID 35892571, 2022). "Recently, intravitreal injection of S100B, which is mainly expressed by astrocytes, was found to cause glaucoma-like neuronal degeneration in the retina and optic nerve." (PMID 34121982, 2021). "Hence, further investigations are necessary to conclude whether synaptic or receptor-associated alterations are relevant previous events followed by RGC loss in these studied S100B-based glaucoma-like models." (PMID 32977518, 2020). "As a result, it can be concluded that S100B-mediated activation of NF-κB and complement pathways plays a vital role in the pathogenesis of glaucoma." (PMID 35892571, 2022). "Our observations provide comprehensive proteomic data to strengthen the pathophysiological impact of S100B and the involvement of the immune system in glaucoma." (PMID 35053014, 2021). "A high autoantibody titer against S100B, a small calcium binding protein, was detected in samples from glaucoma patients." (PMID 35053014, 2021). "In a study of an S100B-induced glaucoma-like animal model, microglia were activated and increased in the optic nerve on day 14, and RGC apoptosis was observed." (PMID 34121982, 2021). "In this current study, we used two different S100B-based glaucoma-like models to determine synaptic alterations before and during neuronal degeneration." (PMID 32977518, 2020). "This was the reason for the usage of a low (13.5 mg/kg body weight) and high minocycline dose (25 mg/kg body weight) for our S100B glaucoma-like model." (PMID 33317557, 2020). "In both of our S100B-based glaucoma-like models, a significantly higher GABA-A receptor α3 signal was found." (PMID 32977518, 2020). "In this S100B glaucoma-like model we can demonstrate that microglia contribute significantly to neuronal degeneration but are not the sole cause of degeneration." (PMID 33317557, 2020). "In previous clinical studies, glaucoma patients showed an increased antibody titer against the protein S100B in their tear film." (PMID 32977518, 2020). "Previous studies noted that intravitreal injection of S100B triggered a glaucoma-like degeneration of retina and optic nerve as well as microglia activation after 14 days." (PMID 33317557, 2020). "Fourteen days after intravitreal injection, RGCs were also damaged, which indicates that the intravitreal S100B model is a glaucoma-like model." (PMID 33317557, 2020). "An increase of autoreactive antibodies against the S100B protein was detectable in the tears of glaucoma patients." (PMID 30319357, 2018). "The relevance of the protein S100B in pathophysiology of glaucoma was also investigated in an animal model." (PMID 30319357, 2018). "Very few glaucoma-related neuroinflammatory and reactive astrocyte genes and pathways were differentially expressed (Hsp70, Hsp90, Hspb1, C2, Tlr4, S100b, Lcn2, H2-T23), and understanding their significance to an overall neuroinflammatory astrocyte requires more focused functional testing." (PMID 37759301, 2023). "Additionally, S100B, a gene encoding a calcium-binding protein which we found enriched in the peripheral RPE has been linked with glaucoma, which can result in loss of peripheral vision." (PMID 36506320, 2022).
glaucoma (continued). "In a glaucoma-like animal model with intraocular S100B injection, RGC death occurs at 14 days." (PMID 32977518, 2020). "In our intravitreal S100B model and in other glaucoma-like models, the microglia are activated." (PMID 33317557, 2020). "Also, patients with glaucoma demonstrate an increase of autoantibodies against S100B in their tear fluid." (PMID 33317557, 2020). "We could demonstrate, for the first time, that a local, intravitreal injection of S100B leads to glaucoma like damage." (PMID 30319357, 2018). "The intraocular injection of S100B is a new model for a glaucoma like degeneration." (PMID 30319357, 2018). "Interestingly, mass spectrometry of the probes revealed a regulation of certain proteins after S100B immunization, which are not directly linked to glaucoma or RGCs, such as IMPG1 and IMPG2." (PMID 35053014, 2021). "Hence, the role of S100B was investigated in glaucoma models." (PMID 33317557, 2020). "The S100β-evoked RGC damage and impaired ocular responses are recovered by minocycline, indicating the role of microglia in triggering glaucoma-like phenotypes." (PMID 36769067, 2023). "In our study, all glaucoma groups displayed disarranged GFAP+ and S100B+ astroglia in their optic nerves." (PMID 36733392, 2022). "Data from human vitreous humor proteomics studies also show that S100B detection in patients with glaucoma runs at only 70% of that in individuals without glaucoma; however, a full understanding of the role of S100B in glaucoma is lacking." (PMID 39908332, 2025).
metastatic disease (12 papers, 2011 to 2025). "As we have previously reported, S100β is an output of a network activated by prolonged exposure to endocrine treatment; therefore, it has the potential to act as a biomarker for the emergence of metastatic disease." (PMID 28399921, 2017). "Given that 40% of the MPNST samples were metastatic tumors collected from the lung, the identification of CLEC10A + and S100B + lung specific DC was expected." (PMID 40585258, 2025). "The authors have shown that S100B and LDH appear to indicate different aspects of metastatic disease." (PMID 40535809, 2025). "The discriminative power of plasma OPN in identifying metastatic disease was not stronger than that of serum S100B, and the AUC values were similar for serum S100B and serum OPN." (PMID 38202181, 2023). "In matched primary and metastatic tumors from patients who had recurred on endocrine therapy (n = 4), S100β was detected in all of the metastatic tumors even if it was absent from the primary tumor tissue." (PMID 28399921, 2017). "In 33 patients with no symptoms but with an increased S100B, metastatic disease was confirmed in twenty three patients (69.7%) and 10 patients were healthy." (PMID 21810220, 2011). "However, one must be aware that normal S‐100B levels do not exclude metastatic disease, emphasizing the importance of thorough self‐inspection by patients and physical examination during follow‐up visits." (PMID 31468535, 2019).
epileptic seizures (11 papers, 2012 to 2025). "We investigated whether mGluR3, an excitatory receptor that is highly associated with S100B activation, was involved in KA-induced epileptic seizures." (PMID 28386293, 2017). "Epileptic seizures are thought to induce inflammation and blood-brain barrier leakage which may be the cause of the increase in MMP-9 and S100B, along with other biomarkers in the serum." (PMID 40076533, 2025). "Thus, increases in the concentration of NSE, VILIP-1, or S100B in the blood serum are regarded as indicators of neuronal death during epileptic seizures as well as of severity of the disease." (PMID 38203674, 2023). "To determine the detailed mechanisms of UR in KA-induced epileptic seizures, we investigated whether UR alters S100B, RAGE, mGluR3, MCP-1, and CCR-2 protein levels 6 weeks after KA injection." (PMID 28386293, 2017). "The counts of S100-B immunoreactive cells in the CA1, CA2, CA3 and hilus regions of the hippocampus increased in KA-induced epileptic seizure rats, and these counts were decreased through the 6-week application of ear ES and EA at ST36–ST37." (PMID 28352122, 2017).